TBX3 (T-box transcription factor 3)
Diseases named in the same sentence as TBX3 in open-access papers (continued):
Sharing a sentence is not in itself a finding about the gene and the disease.
tumor (continued). "Deleting Tbx3 or Usp15 leads to tumor redifferentiation, which parallels their overdifferentiation tendency during development, exemplified by disrupted thyroid folliculogenesis and elevated differentiation factors such as Tpo, Nis, Tg." (PMID 38750011, 2024). "Therefore, TBX3 could be associated with BRAFV600E-related tumor genesis." (PMID 39290709, 2024). "In contrast, the knockdown of TBX3 significantly reduces the number of CSCs in various breast tumor cell lines and diminishes their ability to form tumor spheres." (PMID 38965548, 2024). "Of note, the tumor subset displaying high levels of TBX3 exhibited higher survival length and lower Ki-67 index compared with TBX3-negative tumors." (PMID 38909034, 2024). "In summary, our data demonstrate that TBX3 is overexpressed in a subset of human iCCA samples, and its high expression is associated with decreased MAD2L1 levels, decreased tumor cell proliferation, and prolonged survival." (PMID 38909034, 2024). "Recently, the oncogenic function of TBX3 draws attention, where TBX3 is often up-regulated in tumorigenesis and promotes tumor cell proliferation and metastasis, especially during BRAF/MAPK induced tumorigenesis." (PMID 38750011, 2024). "The literature reports also demonstrate that TBX3 upregulates important gene targets involved in tumor development, angiogenesis and ion transport such as versican (VCAN), CD9, chromo-domain helicase DNA binding protein 1 (CHDR1) and CD86." (PMID 39358558, 2024). "We further noted that mutations targeting TBX3 were confined to EA patients and those targeting the FBXW7 tumor suppressor to AA patients whereas mutations in the ARID1A gene were distinctively enriched among Kenyan patients." (PMID 37902422, 2023). "As expected, conditioned media of primary mPTC tumor cells attracted MDSCs in chemotaxis assay, which was dramatically diminished by Tbx3 removal." (PMID 35332119, 2022). "In summary, our findings uncover a critical role for BRAF/TBX3/CXCLs signaling in the regulation of anti-tumor immunity and suggest the use of combination CXCR2 inhibitor with MAPKi therapy in patients with advanced PTC." (PMID 35332119, 2022). "The abundance of Tbx3 was also continuously up-regulated with tumor progression, supporting its important role in the tumor development." (PMID 35332119, 2022). "Targeting the activated TROY/ p85α/TBX3 axis using the small-molecule PI3K inhibitor wortmannin impairs the tumor stemness properties of HCC cells." (PMID 35610614, 2022). "To clarify if the chemokines were down-regulated by Tbx3 knock-out in tumor cells, we crossed Rosa26-mTmG reporter line into the mPTC animal and obtained mPTCGFP cells through FACS sorting." (PMID 35332119, 2022). "Within tumor cells, TBX3 is one critical factor initiated by BRAFV600E-induced oncogenic signalings and participates in immune environment orchestration." (PMID 35332119, 2022). "Although macrophages, neutrophils, and MDSCs principally respond to CXCR2 ligands and play critical role in tumor immune evasion, MDSCs content was dramatically reduced in mPTC/Tbx3−/− tumors compared with control." (PMID 35332119, 2022). "TBX3 is a member of the highly conserved family of T-box transcription factors involved in embryogenesis, organogenesis and tumor progression." (PMID 31570773, 2020). "Surprisingly, however, when the tumours were excised at the 6 week end point, the Flag-Empty tumours were larger and weighed significantly more than the Flag Tbx3+2a tumours." (PMID 32098189, 2020). "The mice injected with Flag-Tbx3+2a cells developed tumours as early as 4 weeks, whereas tumours were only visible after 5 weeks in mice injected with Flag-Empty cells." (PMID 32098189, 2020). "Our data show that TBX3 promotes substrate-dependent and -independent proliferation, migration and tumour formation." (PMID 32098189, 2020).
tumor (continued). "This study is the first of its kind to report significant functional differences between the two TBX3 isoforms, both in vitro and in vivo, beginning with TBX3iso1-dependent promotion of angiogenesis and resulting in tumor initiation and progression." (PMID 31570773, 2020). "We next investigated the in vivo tumour-forming ability of TBX3 overexpressing cells by injecting RD Flag-Empty and Flag-Tbx3+2a cells subcutaneously into immunocompromised nude mice." (PMID 32098189, 2020). "In conclusion, this study shows that TBX3 promotes substrate-dependent and -independent proliferation, migration and tumour formation of ERMS." (PMID 32098189, 2020). "Compared to control cells, reduced TBX3 levels resulted in a marked increase in tumor growth in vivo, which was reflected in increased tumor weights." (PMID 31910858, 2020). "And TBX2 and TBX3 over-expressions has been elucidated to induce the tumor growth and metastasis, functioning as downstream target gene of Wnt/beta-catenin and pRb pathway through the suppression of p14ARF, p21CIP1, NDRG1 and E-cadherin." (PMID 33447348, 2020). "We demonstrate that a c-Myc/AKT/TBX3-driven process promotes cell proliferation, anchorage-independent growth, cell migration, tumour formation and invasion of ERMS cells." (PMID 32098189, 2020). "Instead, we found that TBX3 acts as a tumor suppressor in RMS, largely due to its repression of TBX2." (PMID 30979887, 2019). "The levels of Tbx3 protein in 8 of the 11 pairs of HCC tissues were dramatically upregulated as compared with the non-tumor tissues." (PMID 30151243, 2018). "HepG2 cells with stable ectopic expression of Tbx3 or Tbx3 mutant were implanted in the spleen, and tumor modules that developed in the liver were examined at the end of the experimental period." (PMID 30151243, 2018). "The ratios of the Tbx3 protein levels between tumors and non-tumor tissues were scanned and quantified." (PMID 30151243, 2018). "In our study, we analyzed the expression of Tbx3 in HCC and paired adjacent non-tumor tissues and discovered that the Tbx3 expression level in the tumor tissues was upregulated compared with that in non-tumor tissues." (PMID 30151243, 2018). "For example, TBX3 had high TSG scores in ER+ (TSG=58%, 6.0% of ER+ samples with coding mutations) and ER− (22%, 2.2%) tumours, and was also significantly mutated relative to the background mutation rate in the TCGA data set7." (PMID 27161491, 2016). "There are also a few studies that have described a tumour suppressor role for TBX3 in cervical, uterine and bladder tumours, glioblastomas and fibrosarcomas." (PMID 27110270, 2016). "Together these results confirm that TBX3 and TBX3+2a have tumour suppressor activity in fibroblasts in vitro." (PMID 26900951, 2016). "While this is the first study to provide a full characterization of a tumour suppressor function for TBX3, there are a few high-throughput studies that have hinted at this possibility." (PMID 26900951, 2016). "For example, the mechanism(s) of repression of CDKN2A, which is alternatively spliced to produce the p16INK4 and p14ARF tumor suppressors, will need to be reexamined for potential post-transcriptional effects of TBX3." (PMID 24675841, 2014). "Previous studies have reported that T-box genes/proteins such as TBX2 and TBX3 are overexpressed in several neoplasms." (PMID 25287937, 2014). "Data in the literature on the overexpression of TBX2 and TBX3 in tumor samples and tumor cell lines vary depending on the reference sample chosen and on the molecular category inspected (DNA, RNA, or protein) but tend to lie in the range of 1.5 to 10-fold." (PMID 25344916, 2014). "DUSP4 is known to regulate cell survival and tumor progression, and overexpression induces senescence downstream of RB/E2F, thus placing CAPERα/TBX3 upstream of another p16/RB effector." (PMID 24876127, 2014). "Tumour sections (c) exhibited significantly stronger cytoplasmic and nuclear Tbx3 staining with respect to the normal tissues (d)." (PMID 23082988, 2012).
tumor (continued). "Quite analogously, recent data has shown that estrogen-treatment of MCF cell cultures induces the expression of Fgf by the ERα-positive majority, maintaining an FGFR/Tbx3 positive tumor initiating cell minority." (PMID 21541292, 2011). "TBX3 has been shown to repress the expression of the tumor suppression gene p14ARF and the murine homologue p19ARF." (PMID 22039763, 2011). "Therefore, we prepared a TMA containing 50 BLCA samples, namely, the Xiangya BLCA TMA, and performed multicolor staining on TBX3+ tumor cells (TBX3+ CK19+), CD8+ T cells, and CAFs (α-SMA+)." (PMID 39897553, 2025). "The IMvigor210 cohort, the largest BLCA immunotherapy cohort reported, indicated that TBX3 expression was significantly higher in patients with a desert immune phenotype, low PD-L1 expression on tumor cells (TC0), and low PD-L1 expression on immune cells (IC0)." (PMID 39897553, 2025). "While CUL3 mutations may compromise its tumor-suppressor function and promote progression, the roles of HMCN1 and TBX3 are less defined." (PMID 41479892, 2025). "It is possible that the cooperation between HOXB13and TBX3 could increase the repression of the transcriptionof a subset of tumor suppressors." (PMID 41164275, 2025). "When considering the family of TBX transcription factors, TBX3 exhibited the highest expression level across the tumor cell types considered, supporting the dual nature of this protein as not only regulator of developmental processes, but also of tumorigenesis." (PMID 40343989, 2025). "Once TBX2 or TBX3 expression is dysregulated, it may be involved in the formation of tumor stemness." (PMID 38965548, 2024). "Thus, USP15 promotes tumor cell proliferation and tumor growth through maintaining TBX3 level and related downstream events." (PMID 38750011, 2024). "Similarly, TBX3, mediated by transforming growth factor-β1, enhances tumor stemness of bladder cancer cells, accelerating malignant progression." (PMID 38911382, 2024). "In this regard, the interaction with tissue- or tumor-specific transcription factors might dictate the net effect of TBX3 in a particular tumor type." (PMID 38909034, 2024). "This property of TBX2 and TBX3 makes it to be an important regulator during the tumor process." (PMID 38965548, 2024). "We thus wonder whether USP15 functions in tumor formation partially through its regulation of TBX3 expression." (PMID 38750011, 2024). "For example, in knockdown and overexpressing cell culture models, the role of T-box transcription factor 3 (TBX3) in promoting the proliferation and migration of HPV-positive cells was validated, and the tumour-promoting activity of TBX3 in CC was shown to be influenced by HPV E6 and E7 signalling." (PMID 39735605, 2024). "TBX3 has been identified as a target of tumor suppressor miR-206." (PMID 38965548, 2024). "TBX3 is generally regarded as an oncogene promoting tumor cell proliferation and metastasis." (PMID 35332119, 2022). "Similarly, in tumor tissues from mPTC-TAM/Tbx3−/− mutants, we detected decreased infiltration of MDSCs and increased ratio of CD8+ T cells: G-MDSCs." (PMID 35332119, 2022). "Indeed, estrogen signaling increased the number of breast CSCs through paracrine FGF/Tbx3 signaling and silencing Tbx3 attenuated tumor sphere formation." (PMID 35145908, 2021). "Furthermore, the average volume of tumours in the mice injected with Flag-Tbx3+2a cells was larger when measured with callipers." (PMID 32098189, 2020). "Recent studies have suggested that TBX3 may also function as a tumor suppressor depending on the cellular context." (PMID 31910858, 2020).
tumor (continued). "Indeed, here we show, using ERMS cell culture models in which TBX3 was either stably overexpressed or knocked down, that it promotes cell proliferation, anchorage-independent growth, tumour formation and cell migration and invasion." (PMID 32098189, 2020). "We speculated that the Tbx3+2a-expressing tumour cells have enhanced migratory/invasive ability, which enabled them to leave the primary tumours as single cells and/or clusters of cells." (PMID 32098189, 2020). "Our results suggested that TBX3 functions as a tumor suppressor in ARMS by repression of TBX2." (PMID 30979887, 2019). "Tbx3, a transcriptional repressor, is essential in the organogenesis of vertebrates, stem cell self-renewal and differentiation, and the carcinogenesis of multiple tumor types." (PMID 30151243, 2018). "Taken together, these data suggest that a high Tbx3 level promotes tumor progression." (PMID 30151243, 2018). "Consistently, ectopic expression of Tbx3 largely promoted tumor metastasis." (PMID 30151243, 2018). "The kinase responsible for phosphorylating TBX3 at SP190 was not identified in this study however, we are currently investigating the possibility that it may be ERK which, like TBX3, can act as either an oncoprotein or a tumour suppressor." (PMID 27110270, 2016). "Furthermore, the overexpression of Tbx3+2a was able to significantly reduce the tumour volume and weight." (PMID 26900951, 2016). "In this study, we created doxycycline inducible double transgenic mice (MMTV-rtTA;tet-myc-TBX3-IRES-Luciferase) to test whether TBX3 over-expression can induce tumor formation within the mammary gland." (PMID 22039763, 2011). "However, TBX3 expression only partially overlapped with that of other Wnt target genes such as AXIN2 and LGR5, suggesting varying levels of Wnt activation across tumor types, and mechanisms of uncoupled regulation between TBX3 and other targets depending on the context." (PMID 40343989, 2025). "However, in human tissue, the correlation between TBX3+ tumor cells and T cells and CAFs remains unclear." (PMID 39897553, 2025). "However, TBX3 acts as a tumor suppressor in other tumor entities, including β-catenin-driven HCC." (PMID 38909034, 2024). "For example, in hepatocellular carcinoma and colorectal cancer, TBX3 expression levels are positively correlated with the grading of cell proliferation markers (Ki-67); further, its high expression is closely related to malignant staging, tumor size, and poor prognosis 20-22." (PMID 38911382, 2024). "Analysis of PTC patient specimens revealed that TBX3 is highly expressed in cancerous thyroid cells, indicating down regulation of TBX3 could delay the G1/S phase transition, decreased cell growth in vitro and inhibited tumor formation in vivo." (PMID 39290709, 2024). "In conclusion, TBX3 may act as a tumor promoter or suppressor, depending on the cellular context." (PMID 38965548, 2024). "TBX3 promotes growth of mammary epithelial cells both in cell culture and in a transgenic mouse where it causes mammary hyperplasia in the absence of tumor formation." (PMID 26579496, 2015). "Furthermore, we show that TBX3 may play an important role as a reciprocal switch between substrate dependent cell proliferation and tumour invasion." (PMID 24098938, 2013). "Through LASSO-Cox regression and stepwise selection, we constructed a four-gene Tumor-Progressing Fibroblast Riskscore model comprising FOXA1, TBX3, LRIG1, and RNF11." (PMID 41624768, 2026). "Although there are some studies indicating TBX3 is an oncogene in BLCA 31,32, the role of TBX3 in the TME and tumor progression is not fully understood." (PMID 39897553, 2025). "TBX3 directly promotes the expression of Inhibitor of DNA binding 1 (ID1), a key regulator of tumor progression, and inhibits E-cadherin expression via the TBX3-ID1-MITF-axis, promoting migration and invasiveness of melanoma cells." (PMID 38965548, 2024).
tumor (continued). "The USP15-TBX3 axis is reactivated during tumorigenesis, and Usp15 knockout prohibits BRAFV600E-driven tumor development in a Tbx3-dependent manner." (PMID 38750011, 2024). "TBX3 generally is considered an oncogene in HCC; however, a recent study found that TBX3 plays a tumor-inhibitory role in HCC." (PMID 38965548, 2024). "The clinical relevance is highlighted in that both USP15 and TBX3 highly correlates with BRAFV600E signature and poor tumor prognosis." (PMID 38750011, 2024). "Thus, it would be critical to determine whether TBX3 plays a role in these tumor subsets." (PMID 38909034, 2024). "Genes TBX3, CASP3, MBNL3, and SEPT2 were enriched in tumor pathways and their AS level changes were confirmed by RT-qPCR experiments." (PMID 38155938, 2023). "Indeed, while large evidence suggests oncogenic roles for TBX341,42,44,45, a few studies have indicated that it may also have tumor suppressor functions, suggesting that TBX3 function may depend on cellular context-specific factors and on its protein partners/regulators." (PMID 38081972, 2023). "As reported for SIRT686, also TBX3 has been described to regulate a plethora of genes, including CSC and tumor progression markers, in a tissue-specific manner." (PMID 38081972, 2023). "This BRAFV600E-induced immune suppression involves re-activation of the developmental factor TBX3, which in turn up-regulates CXCR2 ligands in a TLR2-NFκB dependent manner, leading to MDSCs recruitment into the tumor microenvironment." (PMID 35332119, 2022). "Remarkably, the anti-tumor effects of CD8+ T cells were abrogated specifically in mPTC/Tbx3−/− with recovered tumor growth, since cytotoxic CD8+ T cell were significantly depleted compared to anti-IgG in mPTC/Tbx3−/−." (PMID 35332119, 2022). "In addition, studies which employed knockdown of total TBX3 expression followed by xenotransplantation of cells into mice has revealed that TBX3 is associated with tumor formation, but not whether functional differences exist between isoforms." (PMID 31570773, 2020). "To reveal the expression status of Tbx3 in HCC, we detected the level of Tbx3 protein in 11 paired HCC tumors and adjacent non-tumor tissues by western blot assays." (PMID 30151243, 2018). "One group was associated with rapid proliferation, oxidative phosphorylation, invasiveness, and tumor size (MRPS23, MRPL11, CKS2, LSM3, TBX3, MSN) and another with hypoxia tolerance, anaerobic metabolism, and high lactate content (PDK2, KLF3)." (PMID 17054779, 2006). "Multivariate analysis identified MRPL11, TBX3, and PDK2 expression as independent prognostic gene variables, whereas only tumor volume was identified in a model containing the clinical variables." (PMID 17054779, 2006). "In addition, pathways related to ECM, tumor invasiveness, collagen formation, and TGF-β1 were all significantly activated in the TBX3-overexpression group." (PMID 39897553, 2025). "These analyses indicate that high USP15 expression level could predict higher tumor progression and poorer overall survival, in BRAFV600E related malignancies, presumably due to its regulatory function on TBX3 protein homeostasis." (PMID 38750011, 2024). "Therefore, USP15 maintains TBX3 expression through physiological development and pathological tumor progression where both confine the differentiation progression, as the more USP15/TBX3, the less differentiation, and vice versa." (PMID 38750011, 2024). "As most iCCA samples are TBX3 low and MAD2L1 high, it is tempting to hypothesize that these tumors might be less responsive to the chemotherapy due to the more aggressive tumor cell phenotypes." (PMID 38909034, 2024). "Tumor volume and weight were significantly reduced in mPTC-TAM/Tbx3−/− as well." (PMID 35332119, 2022). "Molecularly, MYC and TBX3 could be partially responsible for ZFHX3′s promoting cell proliferation and tumor growth effects." (PMID 33217982, 2020).